LINC01588 (long independently transcribed non-coding RNA 1588)
Synonyms: C14orf183; LINC01599; C14orf182
Gene: Long non-coding RNA gene on chromosome 14 (49,927,213 to 50,105,121, reverse strand). Ensembl gene ENSG00000214900.
Diseases named in the same sentence as LINC01588 in open-access papers:
LINC01588 is named in the same sentence as 4 diseases in open-access papers, as found by Europe PMC text mining. Sharing a sentence is not in itself a finding about the gene and the disease. The quoted sentences say what the papers report.
pemphigus (1 paper, 2025). Pemphigus is a group of rare autoimmune diseases that cause blistering of the skin and mucous membranes (mouth, nose, throat, eyes, and genitals).This conditioncan occur at any age, but often strikes people in middle or older age. "In pemphigus, an autoimmune skin disease, LINC01588 may epigenetically modulate Th17/Treg equilibrium through the peroxisome proliferator-activated receptor signaling pathway." (PMID 40181954, 2025).
tumor (1 paper, 2022). "Interestingly, the Wilcox test revealed that other survival-related LRLs were highly expressed in the normal samples except AC126773.3, LINC01588, which was highly expressed in the tumor samples." (PMID 35646892, 2022).
LINC01588 also shares sentences with these, for which no sentence is quoted: cancer (1 paper); schizophrenia (1).